SPDEF (SAM pointed domain containing ETS transcription factor)
Diseases named in the same sentence as SPDEF in open-access papers (continued):
Sharing a sentence is not in itself a finding about the gene and the disease.
prostate carcinoma (continued). "The same upregulation of cytokeratin 18 and E-cadherin expression was obtained when CDK11p58 expression was knocked down, further supporting our conclusions that CDK11p58 impacts prostate cancer cell migration and invasion through regulation of SPDEF protein stability." (PMID 26885618, 2016). "Oncogenic activities of Ets fusion proteins in prostate cancer have been studied in detail; however, potential tumor and metastasis suppressor activities of Ets factors have been neglected until recently, when we and others showed that SPDEF is a tumor and metastasis suppressor in prostate cancer." (PMID 26885618, 2016). "Likewise, high SPDEF levels were found in prostate cancer patients who had a prolong response to androgen deprivation therapy." (PMID 25254494, 2014). "Furthermore, re-expression of Foxm1 in SPDEF-expressing cancer cells restored tumor weight in orthotopic mouse model of prostate cancer, coinciding with increased number of Ki-67-positive and PH3-positive tumor cells." (PMID 25254494, 2014). "Finally, an inverse correlation between SPDEF and Foxm1 was found in human prostate cancers using two independent human prostate cancer microarray datasets, GSE21034 and GSE16560." (PMID 25254494, 2014). "Since Foxm1 is up-regulated in mouse and human prostate cancers and is required for prostate carcinogenesis, we tested whether SPDEF inhibits Foxm1." (PMID 25254494, 2014). "Furthermore, an inverse correlation between SPDEF and Foxm1 levels was found in human prostate cancers." (PMID 25254494, 2014). "Our studies may serve as a foundation for the development of new therapeutic approaches in prostate cancer by targeting Foxm1 via SPDEF dependent pathways." (PMID 25254494, 2014). "Indeed SPDEF directly transactivates the E-cadherin gene in prostate cancer." (PMID 26885618, 2016). "Since reduced SPDEF expression/activity is a key driver of metastasis in prostate cancer, we tested our hypothesis that the interplay between GADD45α and CDK11p58 elicits its effects on prostate cancer migration and invasion through modulation of SPDEF expression or activity." (PMID 26885618, 2016). "SPDEF directly interacts with the androgen receptor and functions as a coactivator, enhancing prostate-specific antigen (PSA) expression in LNCaP prostate cancer cells." (PMID 40457266, 2025). "In human prostate cancer patients, the SAM pointed domain containing ETS transcription factor (SPDEF) was recently identified as a novel transcriptional regulator of the cellular senescence-related gene prognostic index (CSGPI)." (PMID 37644339, 2024). "Our studies demonstrate that SPDEF expression is repressed during prostate cancer progression and CRPC development, partly by methylation on CpG islands in the SPDEF." (PMID 37900138, 2023). "In summary, our studies demonstrate that SPDEF expression is decreased during prostate cancer progression and CRPC development, partly by methylation on CpG islands in the SPDEF gene." (PMID 37900138, 2023). "It is already known that SPDEF can block EMT by repressing the transcription of Slug in breast, hepatocellular, bladder, and prostate cancer cells 37-39." (PMID 36276640, 2022). "Utilizing the expression levels from three genes (i.e., PCA3, ERG, and SPDEF), EPI provides a risk score predicting whether a patient presenting for their first biopsy with an equivocal PSA from 2 to 10 ng/mL is likely to have GG2 or greater (high-grade) prostate cancer." (PMID 34593984, 2022). "The urine-exosome signature is derived from genes known to play a role in prostate cancer initiation and progression, including ERG, PCA3, and SPDEF." (PMID 34593984, 2022). "Specifically, AR-mediated activation of SPDEF repressed expression of TGFBI and CCL2, key drivers of prostate cancer metastasis." (PMID 30200227, 2018). "We evaluated the impact of SPDEF and GADD45α on migration and invasion of DU145 prostate cancer cells." (PMID 26885618, 2016).
prostate carcinoma (continued). "Thus, downregulation of SPDEF expression may be critical for prostate cancer progression." (PMID 26885618, 2016). "Our data demonstrate that SPDEF functions as a tumor suppressor in SV40 T antigens and c-Myc-induced prostate cancers by inhibiting tumor cell proliferation via disruption of an auto-regulatory element in the Foxm1 promoter." (PMID 25254494, 2014). "The prostate-specific Nkx3.1 nuclear protein directly inhibits SPDEF and prevents SPDEF-mediated PSA activation, indicating a potential role of SPDEF in prostate cancer." (PMID 25254494, 2014). "The transcription factor SPDEF, which has been reported to suppress metastasis via inhibition of EMT in prostate cancer and is known to have low expression in NEPC compared with CRPC, also demonstrated lower mRNA expression in our AIPC cohort compared with the non-AIPC cohort." (PMID 39859392, 2025). "In this review, we discuss the involvement of key TFs, including the E26 Transformation-Specific (ETS) Family (ERG and SPDEF), NF-κB, Activating Protein-1 (AP-1), MYC, and androgen receptor (AR), in prostate cancer while focusing on the molecular mechanisms involved in prostate cancer development." (PMID 38674385, 2024). "We observed that CpG-islands in the SPDEF gene are hypermethylated in prostate cancer cells that do not express SPDEF." (PMID 37900138, 2023). "The commercial available assay ExoDx Prostate (IntelliScore) (NCT03235687, NCT03031418, NCT04720599, NCT02702856) is based on the detection of three RNAs (PCA3, SPDEF, ERG) in urinary sEVs from prostate cancer patients by quantitative reverse transcription-polymerase chain reaction (RT-PCR)." (PMID 36242076, 2022). "Our data confirmed that the treatment of prostate cancer cells with ENZA enhances the effect of radiation through down-regulation of NKX3-1, ZMIZ1, SPDEF and PDE9A genes and up-regulation of LAT, PTPRN2 and OSBPL10 genes in LNCaP cells, as well as up-regulation of CYP1B1 genes in C4-2 cells." (PMID 31221986, 2019). "Similar effects of CDK11p58 and SPDEF on Cytokeratin 18 and E-cadherin expression were seen in another prostate cancer cell line, PC-3 (data not shown)." (PMID 26885618, 2016). "While its expression changes during prostate carcinogenesis (PCa), the role of SPDEF in prostate cancer remains controversial due to the lack of genetic mouse models." (PMID 25254494, 2014). "However, the expression of SPDEF in prostate cancer cells of African-American Origin has not been investigated." (PMID 37900138, 2023). "Moreover, the mechanisms by which SPDEF expression decreases during prostate cancer progression are not delineated." (PMID 37900138, 2023). "Interestingly, our analysis of prostate cancer (DKFZ, Cancer Cell 2018) showed a significant negative correlation between SPDEF transcripts and Gleason score; patients with higher Gleason scores showed significantly reduced levels of SPDEF (n=119, r=0.4667, p<0.0001)." (PMID 37900138, 2023).
breast carcinoma (44 papers, 2002 to 2026). "Collectively, our results identify SPDEF as a tumor suppressor gene in breast cancer, with decreased expression significantly associated with poor survival, aggressive tumor subtypes, and specific demographic patterns." (PMID 41228349, 2025). "In a study of subtype-specific functions of SPDEF in breast cancer, this TF was seen to associate with DNA repair and TGFβ signaling." (PMID 40723262, 2025). "Within the realm of breast cancer, our results align more closely with those observing anti-oncogenic effects of SPDEF, suggesting that SPDEF loss in breast tissue promotes progression, particularly in aggressive tumor subtypes." (PMID 41228349, 2025). "FOXA1, GATA3 and SPDEF are key drivers of estrogen receptor-positive (ER+) breast cancer risk as well as cancer progression." (PMID 34712617, 2021). "SPDEF is normally expressed in a range of epithelial cell types, especially in hormone-regulated tissues, and has been associated with cancer: SPDEF is overexpressed in breast cancer cells but is often lost in high-grade, invasive tumours." (PMID 27997592, 2016). "We therefore chose to focus on FOXA1 for experimental validation of our results, and also SPDEF because it is a less well-studied, newly-identified ER+ breast cancer risk TF." (PMID 27997592, 2016). "We applied the MINDy (Modulator Inference by Network Dynamics) algorithm to four TFs (ESR1, FOXA1, GATA3 and SPDEF) that are key drivers of estrogen receptor-positive (ER+) breast cancer risk, as well as cancer progression." (PMID 27997592, 2016). "Through analysis of tumor samples from over 1200 patients, we demonstrated that low SPDEF levels were linked with worse survival across breast cancers, with the most profound changes seen in Basal tumors, younger patients, and Black or African American patients." (PMID 41228349, 2025). "This study provides compelling evidence that SPDEF functions as a tumor suppressor in breast cancer, particularly among tumors of Basal cells, with low expression strongly associated with adverse clinical and molecular outcomes." (PMID 41228349, 2025). "Background/Objectives: Breast cancer is a heterogeneous disease, and the role of the transcription factor SPDEF remains controversial." (PMID 41228349, 2025). "In the realm of breast cancer, the functional significance of SPDEF remains distinctly controversial, with evidence supporting both tumor-suppressive and oncogenic functions." (PMID 41228349, 2025). "These insights underscore the prognostic and therapeutic relevance of SPDEF and its epigenetic modifiers, paving the way for novel biomarker-driven strategies and epigenetic interventions in breast cancer management." (PMID 41228349, 2025). "SAM pointed domain ETS factor (SPDEF) was considered to have both oncogenic and tumor-suppressive effects in breast cancer." (PMID 35875026, 2022). "Conversely, the down‐regulation of SPDEF in invasive basal breast cancer cell lines supports a tumour suppressive role." (PMID 34191390, 2021). "The ETS family member, SPDEF, exhibits high expression in prostate epithelium and has been shown to promote luminal breast cancer gene expression and proliferation." (PMID 33980863, 2021). "GRIK3 promotes epithelial-mesenchymal transition by regulating the SPDEF/CDH1 signaling in breast cancer cells." (PMID 33717664, 2021). "Conversely, in ER+ breast cancers, SPDEF mRNA is overexpressed and correlates with poor overall survival." (PMID 30200227, 2018). "Similar to other ESE members, the role of SPDEF in breast cancer also varies according to the molecular subtype of the disease." (PMID 30200227, 2018). "In view of the fact that C1orf64 was markedly repressed by AR activation and SPDEF was the only AR-induced gene in the tested subset, these two genes were selected to further examine as possible direct targets of AR in breast cancer cells." (PMID 28915724, 2017).
breast carcinoma (continued). "Collectively, these findings suggest that C1orf64 and SPDEF are direct transcriptional targets of AR in breast cancer." (PMID 28915724, 2017). "This suggests that proliferation of the ER+ breast cancer cell lines was dependent on SPDEF and FOXA1 activity." (PMID 27997592, 2016). "We have found and validated novel modulators of FOXA1 and SPDEF, both of which are of special interest in breast cancer." (PMID 27997592, 2016). "The epithelium-specific Ets transcription factor, SPDEF, plays a critical role in metastasis of prostate and breast cancer cells." (PMID 26885618, 2016). "Whereas, SPDEF overexpression has been shown to inhibit breast cancer cell growth and reduce invasion and migration, other studies indicate that SPDEF overexpression induces invasion and migration in breast cancer cells." (PMID 26885618, 2016). "SPDEF is also a luminal epithelial lineage-specific transcription factor in the breast and has been shown to promote the survival of ER+ breast cancer cells." (PMID 26738740, 2016). "Previous studies demonstrated that both FOXA1 and SPDEF are required for proliferation of ZR751 ER+ breast cancer cells." (PMID 27997592, 2016). "SPDEF, a target gene of ESR1, overexpressed in breast and other solid tumors, was shown to be associated with worse outcomes in patients with ER+ breast cancers and to be critical for the survival of ER+ breast cancer cells in vitro." (PMID 26618778, 2015). "SPDEF was upregulated in ER+ breast cancer cell models of estrogen-deprivation resistance and tamoxifen resistance." (PMID 26618778, 2015). "Expression of SPDEF in vitro in either PC3 prostate or MDA-MB231 breast carcinoma cells decreased cellular proliferation and increased apoptosis." (PMID 25254494, 2014). "Moreover, subtype-specific impacts of gene expression on tumorigenesis have been reported, further complicating efforts to define SPDEF as a prognostic biomarker for breast cancer." (PMID 41228349, 2025). "SPDEF expression and methylation status may serve as prognostic biomarkers across breast cancers, reflecting adverse clinical outcomes and aggressive molecular behavior." (PMID 41228349, 2025). "For example, SPDEF is a protein whose function is dependent on the breast cancer subtype." (PMID 35906698, 2022). "Similarly, transcription factor FOXA1 is essential in a subset of lung and breast cancers but shows a breast-specific functional interaction with ETS family transcription factor SPDEF." (PMID 35768873, 2022). "In cancer literatures, the role of SPDEF in BC is controversial depends on different subtypes, as several studies have demonstrated that high SPDEF expression was confirmed to promote Luminal BC differentiation and correlates with poor overall survival in ER+breast cancer patients." (PMID 34191390, 2021). "In the real data analyses we observed many pairs might have a gene in common, for instance, SPDEF in the breast cancer dataset and BCLAF1 and CDH3 in the lung cancer dataset." (PMID 32334509, 2020). "Furthermore, FOXA1, GATA3, ESR1 and SPDEF are reported as master regulators in FGFR2 signaling and breast cancer risk in ER+ cells." (PMID 29741575, 2018). "Interestingly, C1orf64 shows a strong correlation with SPDEF expression in breast cancer at a level similar to that observed with AR." (PMID 28915724, 2017). "We have identified 36 TFs whose regulons are significantly enriched for genes associated with breast cancer risk loci (termed “risk TFs”), and four of these risk TFs (ESR1, FOXA1, GATA3 and SPDEF) have been identified as MRs of FGFR2-mediated risk in breast cancer." (PMID 27997592, 2016). "Moreover, reduced SPDEF protein expression during prostate and breast cancer progression has been attributed to dysregulated miRNAs." (PMID 26885618, 2016). "miR-510 targets SPDEF, which have been found underexpressed in OC compared with breast carcinoma." (PMID 24512620, 2014). "SPDEF was found to be required for tumorigenesis in ER-positive subset of breast cancers." (PMID 25254494, 2014).
breast carcinoma (continued). "Furthermore, the overexpression of SPDEF increases breast cancer progression." (PMID 31221986, 2019). "The clinical relevance of SPDEF methylation is further supported by prior studies using MSRE-qPCR in other cancers (e.g., ITGA6 in breast cancer, DOK7 in gastric cancer)." (PMID 40457266, 2025). "The downregulated genes (ESR1, AR, SPDEF, and FOXA1) participate in hormone receptor signaling and epithelial integrity in breast cancer." (PMID 41462902, 2025). "In total, seven TFs (HOXC11, FOXA1, SPDEF, SOX12, HOXC10, GATA3 and TFAP2A) were annotated to the breast cancer samples." (PMID 34712617, 2021). "Studies found that many genes unexpectedly enriched in mucin-producing gastrointestinal, pancreatic, and breast cancer showed significant differences in IMAs, including FOXA3, SPDEF, etc.." (PMID 33568091, 2021). "Heterogenous expression of SPDEF and CDH1 counteracted the migration and invasion abilities, respectively, of breast cancer cells induced by GRIK3." (PMID 30977227, 2019). "Taken together, these results indicate that SPDEF/CDH1 signaling is required for the GRIK3‐mediated cell proliferation, migration, and invasion of breast cancer cells." (PMID 30977227, 2019). "Both SPDEF and FOXA1 mRNA and protein were expressed in all three ER+ breast cancer cell lines, and their expression levels were significantly reduced following transfection of siRNA against the TFs." (PMID 27997592, 2016). "We first characterised SPDEF and FOXA1 expression and activity in three ER+ breast cancer cell lines (MCF-7, T47D and ZR751)." (PMID 27997592, 2016). "SPDEF (ranked 1) contains the ETS DNA binding domain, a subtype of the bHLH domain; functions of this gene product are vital for normal development as well as for the survival of breast cancer cells." (PMID 37297004, 2023). "Our data show that the expression of POLR3G in breast cancer samples was negatively correlated with that of eight out of ten genes (GATA3; XBP1; AGR2; SIDT1; AR; SPDEF; FOXA1; MLPH) in a list of signature genes most differentially expressed in luminal A compared to basal-like tumors." (PMID 36497214, 2022). "Finally, based on co-expression network analysis, we screened 7 potential gene markers related to metabolic characteristic index, of which CLCA2, REEP6, SPDEF, and CRAT can be used to indicate breast cancer prognosis." (PMID 35875026, 2022). "In conclusion, our analysis of the effect of potential modulators of SPDEF and FOXA1 activity in ER+ breast cancer suggests that MINDy and other such computational tools have the power to identify valid modulators of TF activity that warrants further follow-up work." (PMID 27997592, 2016). "In contrast, the HB2 cell line is a human mammary epithelial cell line with hardly detectable levels of SPDEF and very low levels of FOXA1 compared with ER+ breast cancer cell lines, whose growth does not depend on SPDEF and FOXA1 activity." (PMID 27997592, 2016). "As the SPDEF/CDH1 pathway is involved in mechanisms regulating cell‐cell adhesions, mobility, and proliferation of epithelial cells and suppressed breast cancer metastasis through epithelial‐mesenchymal transition (EMT), we hypothesized that GRIK3 might play an important role in EMT." (PMID 30977227, 2019). "Through the abstraction of genomic data from The Cancer Genome Atlas Breast Cancer (TCGA BRCA) tumor registry, we show that SPDEF downregulation serves as a negative prognostic indicator in breast cancer with varying significance across molecular and demographic subtypes." (PMID 41228349, 2025).